WT1 (WT1 transcription factor)
Diseases named in the same sentence as WT1 in open-access papers (continued):
Sharing a sentence is not in itself a finding about the gene and the disease.
Diffuse mesangial sclerosis (14 papers, 2011 to 2025). Thickening and scarring (sclerosis) of the mesangium (a structure in the glomerulus). "Wt1 is also a key regulator of podocyte function, and reduced Wt1 expression can cause crescentic glomerulonephritis or mesangial sclerosis depending on gene dosage." (PMID 30939177, 2019). "Dominant mutations in WT1 are associated with the Denys-Drash and Frasier syndromes, characterized by glomerulopathy, mesangial sclerosis, male pseudohermaphroditism, and nephroblastoma." (PMID 21904677, 2011). "However, another report suggested that reduced expression levels of WT1 cause glomerulonephritis and mesangial sclerosis, depending on the level of the protein." (PMID 28299339, 2017). "Additionally, studies using mice models have hypothesized that reduced WT1 expression may lead to mesangial sclerosis of the glomeruli and eventual ESRF, implicating that WT1 deletion may contribute to the development of ESRF." (PMID 39272909, 2024).
lung adenocarcinoma (14 papers, 2013 to 2025). A carcinoma that arises from the lung and is characterized by the presence of malignant glandular epithelial cells. "Since WT1 is highly overexpressed in MPM, while its expression in lung adenocarcinoma is exclusively low, pathologists currently routinely use immunohistochemical (IHC) expression of WT1 for pathologic diagnosis of MPM." (PMID 29100432, 2017). "Moreover, the Western blot analysis performed within this investigation revealed that WT1 protein had mainly cytoplasmic expressions in lung adenocarcinoma cells (only two cases investigated)." (PMID 35453662, 2022). "Molecular diagnostics frequently employ biomarkers such as calretinin, CK5/6, WT‐1, mesothelin (MSLN), and D2‐40, whereas lung adenocarcinoma biomarkers typically include TTF‐1, napsin A, CEA, BerEP4, and claudin‐4." (PMID 40904706, 2025). "The IMIG guideline has suggested the use of Calretinin, D2–40, WT1, and CK5/6 as mesothelial markers, TTF-1, Napsin-A, Claudin 4, CEA as lung adenocarcinoma markers p40, p63, CK5/6, MOC-31 as squamous cell markers." (PMID 29317712, 2018). "WT1 is not presented in lung adenocarcinomas or squamous cell carcinomas; thus, it is useful in differentiating these malignancies from epithelioid mesothelioma." (PMID 38280040, 2024).
lymphoma (14 papers, 2014 to 2025). A malignant (clonal) proliferation of B- lymphocytes or T- lymphocytes which involves the lymph nodes, bone marrow and/or extranodal sites. "Other unusual circumstances contributing to misinterpretation include a include a synaptophysin, chromogranin and CD56 (keratin, desmin and WT1 negative) mesenteric ES (EWSR1-FLI1 positive) and numerous tumor-associated lymphocytes in an ELS originally diagnosed as lymphoma." (PMID 34698236, 2021).
non-small cell lung carcinoma (14 papers, 2013 to 2025). A group of at least three distinct histological types of lung cancer, including non-small cell squamous cell carcinoma, adenocarcinoma, and large cell carcinoma. "WT1 gene is expressed highly abnormally in a variety of tumors, including breast, thyroid, non-small cell lung cancers, and HNSCC, and is considered to have the characteristics of an oncogene." (PMID 34257533, 2021). "Furthermore, increased cell proliferation induced by WT1 has been shown in several other types of cancer cells including non-small cell lung cancer and several solid cancer cells." (PMID 25929687, 2015). "Patients treated with the WT1-235 CTL peptide vaccine included 43 and 13 with malignant glioma and non-small-cell lung cancer, respectively." (PMID 36672344, 2023). "However, the role of WT1 in non-small-cell lung cancer (NSCLC) carcinogenesis remains unclear." (PMID 23936312, 2013).
chronic kidney disease (13 papers, 2009 to 2026). Impairment of the renal function secondary to chronic kidney damage persisting for three or more months. "Pathogenic variants in the Wilms’ tumor suppressor gene 1 (WT1 gene) can lead to serious disorders within the kidney and urogenital system, including chronic kidney disease." (PMID 40332152, 2025). "Although we were unable to assess renal defects in Pcdhg@ null mice, we did examine postnatal kidney from heterozygous Pcdhg@ mutant mice, as heterozygous mutations of developmental genes such as Wt1 have been shown to result in end-stage renal disease." (PMID 19956686, 2009). "A wide spectrum of renal symptoms, including oncogenic characteristics, may result from WT1 expression dysfunction, ultimately leading to chronic kidney disease (CKD)." (PMID 40332152, 2025). "Chronic kidney disease stage ≥3 renal impairment was exclusively seen in unplanned PICU admitted patients, with ESKD occurring in two patients, both with bilateral WT, of which one had a WT1 gene variant." (PMID 35205701, 2022). "In this model, the mesenchymal-to-epithelial transition and the expression of nephron markers (e.g., Nephrin, WT1) were observed, indicating its potential utility for drug screening in chronic kidney disease (CKD)." (PMID 40989835, 2025). "We evaluated the predictive value of immunohistochemical staining for α-smooth muscle actin (SMA), Wilm’s tumor 1 (WT1), CD68, and cytokeratin for end-stage renal disease (ESRD)." (PMID 23773275, 2013). "We examined WT1 in uE (uE-WT1), along with other urine markers of glomerular and kidney tubule injury, in individuals without chronic kidney disease (CKD)." (PMID 37795410, 2023). "Similarly, in a mouse chronic kidney disease model given an intravenous injection of human GFP(+)-Muse cells, no human/mouse probe double-positive cells among the GFP(+)/WT1(+) cells were observed in the glomerulus." (PMID 33924240, 2021).
endometrial cancer (13 papers, 2012 to 2025). Primary or metastatic malignant neoplasm involving the endometrium (mucous membrane that lines the endometrial cavity). "In the present paper, we conducted a systematic meta-analysis with the aim to elucidate the diagnostic and prognostic role of WT1 immunoexpression in patients with endometrial carcinoma." (PMID 32859123, 2020). "The variant frequency for WT1 was fourth in endometrial cancer and sixth in CRC, while FAT1 was second in endometrial cancer and seventh in CRC." (PMID 40627234, 2025). "The product of Wilms tumor gene 1 (WT1) has been determined to be a TAA with therapeutic promise for endometrial cancer." (PMID 37511876, 2023). "To date, on the other hand, only few reports are available on the prognostic impact of WT1 expression in endometrial cancer patients." (PMID 32859123, 2020). "Nevertheless, the clinical-prognostic implications of WT1 expression in endometrial cancer are still controversial." (PMID 32859123, 2020). "Nonetheless, they included several genes with known functional roles in ovarian and/or endometrial cancers as well as the common immunohistochemical biomarker, WT1, that is used to distinguish ovarian serous and endometrial serous adenocarcinomas." (PMID 22371431, 2012). "Yet other biomarkers, such as WT1, are specific to only a single histologic subtype within either ovarian or endometrial cancers." (PMID 22371431, 2012). "Additionally, there is genetic overlap between UL and endometrial cancer, with implicated genes including CLPTM1-like (CLPTM1L), microRNA 4457 (MIR4457), TERT, WT1 transcription factor (WT1), and WT1 antisense RNA (WT1-AS)." (PMID 38790186, 2024). "Therefore, to better clarify this issue, we conducted a systematic review and meta-analysis, including all published papers on the WT1 immunohistochemical expression across all histotypes of endometrial carcinoma." (PMID 32859123, 2020). "On the other hand, HAND2-AS1, PEG3, OGN, SFRP4, WT1, FOXL2 and EFEMP1 were significantly lower in endometrial cancer tissues than in normal tissues." (PMID 32555395, 2020). "However, recent papers showed that WT1 immunoexpression can be observed in different histotypes of endometrial carcinoma also suggesting that WT1 may represent a potential prognostic marker in endometrial carcinoma." (PMID 32859123, 2020).
gonadoblastoma (13 papers, 2012 to 2025). A mixed germ cell/sex cord-stromal tumor characterized by the presence of large germ cells which resemble seminoma cells and small cells which resemble Sertoli or granulosa cells. "Gonadoblastoma was reported in 4 patients, including 1 patient (aged 23 years) with an intron 9 splice-site variant who also had a dysgerminoma, 1 patient with a WT1 deletion at the age of 8 months, and 2 patients with missense variants in exon 9 (aged 1 and 3 years)." (PMID 39698353, 2024). "Other malignancies that may occur less frequently in patients with WT1 variants include germ cell tumors, such as gonadoblastoma." (PMID 39698353, 2024). "FS, a rare disorder caused by variants of the donor splice site located in intron 9 of WT1, is characterized by kidney diseases such as steroid-resistant nephrotic syndrome (SRNS), external genitalia, and gonadoblastoma." (PMID 38877226, 2024). "Risk of gonadoblastoma is high when the early stage of Sertoli cell differentiation is disrupted by mutations in SRY, WT1, SOX9, DMRT1, FOG2/GATA4, FGF9 etc.." (PMID 28825592, 2018).
osteosarcoma (13 papers, 2004 to 2025). A usually aggressive malignant bone-forming mesenchymal neoplasm, predominantly affecting adolescents and young adults. "In particular, WT1 seems to be associated with very poor survival of patients with osteogenic sarcoma metastasis even if WT1 expression activation would appear linked to metastatic heterogeneity scheme which governs OS." (PMID 28107196, 2017). "The antiapoptotic function of WT1 is not limited to fibroblasts in pulmonary fibrosis, as high WT1 expression in osteosarcoma has been shown to promote BCL2 levels and resistance to apoptosis." (PMID 40493404, 2025). "WT1 has also induced apoptosis of the primary osteosarcoma cells through activation of the proapoptotic gene Bak33." (PMID 35610319, 2022). "Six cases of conventional high-grade osteogenic sarcoma were screened to verify WT1 expression and the protein was expressed exclusively in three cases." (PMID 28107196, 2017). "According to a previous report, WT1 (−KTS) induced apoptosis by up-regulating caspase 3 in osteosarcoma cells." (PMID 25491731, 2014). "In conclusion, WT1 acts as a tumour promoter in osteosarcoma and it could be a potential therapeutic target." (PMID 28107196, 2017). "Furthermore, expression of WT1 in osteosarcoma cell lines, Saos-2 and U20S can alter signaling pathways and induce apoptosis, and plasmid-mediated transfection of WT1-KTS isoforms into in HCC cell lines, Hep3B and HepG2 also induced apoptosis." (PMID 22244202, 2012). "We used clones of human osteosarcoma cell lines Saos-2 and U2OS with tetracycline-repressible isoforms of WT1." (PMID 40613901, 2025). "A high WT1 expression level was described in various types of human bone and soft-tissue sarcomas, including osteosarcoma (OS), but its function in carcinogenesis is not yet well understood." (PMID 28107196, 2017). "Nevertheless, experimental overexpression of WT1 in SAOS osteosarcoma cells did not influence GP210 mRNA expression." (PMID 15613247, 2004). "However, experimental tetracycline dependent induction of WT1 in SAOS osteosarcoma cells did not influence GP210 transcription." (PMID 15613247, 2004). "Experimentally we found that WT1 does not influence GP210 expression in human osteosarcoma cells." (PMID 15613247, 2004).
renal carcinoma (13 papers, 2017 to 2025). A carcinoma arising from the epithelium of the renal parenchyma or the renal pelvis. "Dysregulation of WT1 is linked to a paediatric renal cancer and leads to abnormalities in the urogenital tract, suggesting that WT1 is essential for proper kidney development and the health and maintenance of a functioning glomerulus." (PMID 30518571, 2018). "Experimental analysis showed that WT1 overexpression inhibited the proliferation of renal carcinoma A498 cells and promoted arrest at the G2/M checkpoint." (PMID 35915803, 2022). "The conclusion of a WT1/IL-24 regulatory axis indicates the importance of WT1 in regulating the renal cancer microenvironment." (PMID 35915803, 2022). "This study provides the first evidence that WT1 overexpression induces G2/M cell cycle arrest via upregulating IL-24 expression and inhibits human renal carcinoma cell proliferation." (PMID 35915803, 2022). "The findings suggest that the WT1/IL-24 regulatory axis may be essential as a regulator of cell proliferation and may thus represent an attractive target for renal carcinoma prevention and treatment." (PMID 35915803, 2022). "Therefore, in this study, we evaluated the ability of WT1 to block proliferation in renal carcinoma cells in vitro." (PMID 35915803, 2022). "Similarly, the WT1 repressor downregulated TERT transcription in a renal carcinoma cell line where overexpression of WT1 suppressed both TERT and MYC mRNA levels via binding to their promoters." (PMID 33802026, 2021). "However, the exact roles and the mechanisms of WT1 in renal carcinoma are not well understood." (PMID 35915803, 2022).
endometrioid carcinoma (12 papers, 2014 to 2025). "Of note, WT1 has also been reported positive in more than 90% in adenomatoid tumors, 76% ovarian sex cord-stromal tumor, 77% serous papillary carcinoma of the ovary, and 29% of endometrioid carcinoma." (PMID 24860692, 2014). "On the other hand, if WT1 is negative, PgR expression suggests endometrioid carcinoma." (PMID 38573494, 2024). "Borderline seromucinous tumors and endometrioid carcinoma with mucinous differentiation are usually positive for IHC stains CK7, ER, PR and CA125 as well as PAX8 and are usually negative for CK20, CDX2 and WT1." (PMID 33736662, 2021).
epithelioid mesothelioma (12 papers, 2013 to 2026). "In the phase I/II MESODEC trial (estimated study completion in 2025), vaccination with autologous DCs loaded with the mRNA encoding for the WT1 TAA (WT1/DC) has been combined with standard chemotherapy for the first-line treatment of epithelioid mesothelioma." (PMID 40918456, 2025). "WT1 expression was present in 56 (86.2%) epithelioid mesothelioma, with the immunohistochemical score of 3+ in 32 cases." (PMID 29317712, 2018). "This immunoprofile is diagnostic for epithelioid mesothelioma and is crucial for excluding other mimics, such as serous papillary carcinoma of the peritoneum or ovary (typically WT1 positive but calretinin negative) or metastatic adenocarcinoma (typically CK20 and/or CEA positive)." (PMID 41246574, 2025). "Laparoscopic palliative tumor resection and peritoneal effusion drainage were performed, and postoperative pathology/immunohistochemistry (CK+, CR+, CK5/6+, D2-40+, WT1+, CD20-, CDX2-) confirmed epithelioid mesothelioma of the omentum." (PMID 41970397, 2026). "Immunohistochemistry was pivotal in diagnosis, with tumour cells in both peritoneal and gallbladder tissues staining positively for D2–40, WT1, CK7, and CK5/6, and negatively for BerEP4, confirming metastatic epithelioid mesothelioma." (PMID 40585446, 2025). "A laparoscopic biopsy confirmed malignant epithelioid mesothelioma, supported by immunohistochemical positivity for cytokeratin 7 (CK7), calretinin, and Wilms tumor 1 (WT1)." (PMID 41246574, 2025). "Peritoneal biopsy showed neoplastic cells which stained positively on immunohistochemistry with D2–40 (podoplanin), WT1 (Wilms tumour-1), Cytokeratins 7 and 5/6 (CK7 and CK5/6) but negatively with BerEP4, consistent with metastatic malignant epithelioid mesothelioma." (PMID 40585446, 2025). "In our first case of epithelioid mesothelioma, the neoplastic cells showed cytokeratin 5/6 (CK5/6), calretinin, and Wilms‐tumor‐1 (WT1) expression, while remaining negative with thyroid transcription factor‐1 (TTF‐1)." (PMID 36808895, 2023).
hepatocellular carcinoma (12 papers, 2008 to 2024). A malignant tumor that arises from hepatocytes. "In hepatocellular cancer, WT1‐mediated LEF1 transcription is repressed by mangiferin, which controls β‐catenin‐independent Wnt signaling inactivation." (PMID 39479608, 2024). "In another study, hepatocellular carcinoma cells were transfected with dsRNA by liposomes targeting the Wilms’ tumor 1 (WT1) gene promoter, which upregulated WT1, a potent tumor suppressor, and resulted in increased apoptosis of malignant cells." (PMID 29471827, 2018). "Recently, some studies showed WT1 is expressed in several human hepatocellular carcinoma (HCC) cell lines, and is also expressed in tumor tissue in 42% of patients with HCC." (PMID 22244202, 2012). "In this study, we focus on investigating the effects and efficacy of WT1 induction by small dsRNA in the treatment of hepatocellular carcinoma." (PMID 22244202, 2012). "In this study, we investigate the effects of the dsRNA that specifically targets the promoter region of WT1 on the growth of human hepatocellular carcinoma cells HepG2." (PMID 22244202, 2012). "The present study was conducted to evaluate the potential of WT1 induction by small activating RNA targeting the WT1 promoter (dsWT1) in the treatment of hepatocellular carcinoma." (PMID 22244202, 2012). "Human hepatocellular carcinoma (HCC) cells express WT1 and/or carcinoembryonic antigen (CEA) as potential targets for the induction of antitumor immunity." (PMID 18793383, 2008). "The results revealed a new way of inhibiting hepatocellular cancer through Wnt signaling that was independent of β‐catenin and controlled by WT1‐associated LEF1 suppression." (PMID 39479608, 2024). "For example, RNAa-mediated overexpression of WT1 may have therapeutic potential in hepatocellular carcinoma." (PMID 24489730, 2014). "Mžik M., Chmelařová M., John S., Laco J., Slabý O., Kiss I., BohovicováL., Palička V., Nekvindová J. Aberrant methylation of tumoursuppressor genes WT1, GATA5 and PAX5 in hepatocellular carcinoma.Clin." (PMID 36714033, 2022). "Interestingly, the effect of WT1 expression on apoptosis of hepatocellular carcinoma cells seems to be specific to doxorubicin, and not to other chemotherapeutic agents." (PMID 26573232, 2016). "It is reported that WT1 is expressed in several human hepatocellular carcinoma (HCC) cell lines, including PLC/PRF/5 and HepG2, and in HCC tumor tissue in a high proportion of patients, up-regulation of WT1 in liver cells promotes apoptosis resistance and cellular dedifferentiation." (PMID 22244202, 2012).